NPPC (natriuretic peptide C)
Description:
[CNP-22]: Hormone which plays a role in endochondral ossification through regulation of cartilaginous growth plate chondrocytes proliferation and differentiation (By similarity). May also be vasoactive and natriuretic. Acts by specifically binding and stimulating NPR2 to produce cGMP. Binds the clearance receptor NPR3.
Synonyms: CNP2; CNP
Tractability: Antibody: its Gene Ontology location is reachable by antibodies, with high confidence; UniProt places it where antibodies can reach, with medium confidence; UniProt predicts a signal peptide or a membrane-spanning region.
Gene: Protein-coding gene on chromosome 2 (231,921,809 to 231,926,396, reverse strand). Ensembl gene ENSG00000163273.
Subcellular location: Secreted
Pathways (Reactome):
Muscle contraction: Physiological factors
Gene Ontology:
Molecular function: hormone activity; hormone receptor binding; signaling receptor binding
Biological process: cGMP biosynthetic process; negative regulation of meiotic cell cycle; negative regulation of oocyte maturation; protein folding; receptor guanylyl cyclase signaling pathway; growth plate cartilage chondrocyte differentiation; growth plate cartilage chondrocyte proliferation; angiogenesis; blood vessel remodeling; c-di-GMP signaling; cellular response to glycoprotein; chromosome organization; cumulus cell differentiation; gastric emptying; intracellular calcium ion homeostasis; meiotic cell cycle process involved in oocyte maturation; multicellular organismal locomotion; negative regulation of cell population proliferation; negative regulation of collagen biosynthetic process; negative regulation of DNA biosynthetic process; negative regulation of neuron apoptotic process; oocyte development; ovarian follicle development; positive regulation of osteoblast differentiation; regulation of smooth muscle cell proliferation; and 8 more
Cellular component: extracellular region; protein-containing complex; secretory granule
Genetic constraint (gnomAD): Loss-of-function variants: 4 observed, 8.83 expected, observed/expected ratio (o/e) 0.45, 90% interval 0.22 to 1.04. That is too few expected variants to judge how well the gene tolerates losing a copy. Missense variants: 182 observed, 155.75 expected, observed/expected ratio (o/e) 1.17, 90% interval 1.03 to 1.32. Synonymous variants: 83 observed, 74.88 expected, observed/expected ratio (o/e) 1.11, 90% interval 0.93 to 1.33.
Homologues: Orthologues: chimpanzee NPPC (99% identical), macaque NPPC (98% identical), dog NPPC (96% identical), pig NPPC (96% identical), rat Nppc (94% identical), mouse Nppc (91% identical), guinea pig NPPC (89% identical), tropical clawed frog nppc (56% identical), zebrafish nppcl (27% identical), zebrafish nppcl2 (25% identical).
Diseases named in the same sentence as NPPC in open-access papers:
NPPC is named in the same sentence as 54 diseases in open-access papers, as found by Europe PMC text mining. Sharing a sentence is not in itself a finding about the gene and the disease. The quoted sentences say what the papers report.
achondroplasia (24 papers, 2015 to 2026). Achondroplasia is the most common form of chondrodysplasia, characterized by rhizomelia, exaggerated lumbar lordosis, brachydactyly, and macrocephaly with frontal bossing and midface hypoplasia. "Patients harbouring mutations in genes encoding C-type natriuretic peptide (CNP; NPPC) or its receptor guanylyl cyclase B (GC-B, NPR2) suffer from severe growth phenotypes; loss-of-function mutations cause achondroplasia, whereas gain-of-function mutations cause skeletal overgrowth." (PMID 33499110, 2021). "Targeted disruption of the Nppc or Npr2 genes (encoding CNP and GC-B, respectively) lead to achondroplasia, dwarfism, female infertility and early death, and these severe growth phenotypes in mice are mirrored by the symptoms of human patients with inactivating mutations in NPR2 and NPPC mutations." (PMID 33499110, 2021). "Besides that, a CNP analog named vosoritide, that has been used as an experimental drug for the treatment of achondroplasia, can be in the future an option to treat children with nonsyndromic short stature, especially those with heterozygous mutations in the NPR2 or in the NPPC genes." (PMID 30864634, 2019).
dwarfism (5 papers, 2006 to 2022). "Up to now no mutation or loss of the NPPC gene associated with dwarfism has been reported in humans." (PMID 23805197, 2013).
pulmonary arterial hypertension (3 papers, 2018 to 2025). Pulmonary arterial hypertension (PAH) is a group of diseases characterized by mean pulmonary artery pressure >20 mmHg and elevated pulmonary arterial resistance leading to right heart failure. "C-type natriuretic peptide could ameliorate lipopolysaccharide-induced cardiac dysfunction and restore hemodynamic deterioration in rats with pulmonary arterial hypertension." (PMID 30671449, 2018).
developmental delay (1 paper, 2020). "Here, we describe a case of a 4-year-old boy with a de novo 2q36.3q37.1 deletion encompassing TRIP12 and NPPC who presented with severe developmental delay, extremely short stature, small hands, dysmorphic facial features, hearing loss, and epilepsy." (PMID 32528716, 2020). "Thus, genes other than TRIP12 and NPPC located in the deletion region might have contributed to the exaggerated phenotypes in terms of developmental delay and short stature." (PMID 32528716, 2020).
macrodactyly (1 paper, 2019). "The ligand for the receptor is C-type natriuretic peptide (CNP) and overproduction due to translocation of the NPPC gene also caused tall stature with macrodactyly and skeletal dysplasia." (PMID 31555216, 2019).
pituitary tumours (1 paper, 2021). "Our previous studies described the expression of NPPC and NPR2 in a range of human pituitary tumours, normal human pituitary, and normal fetal human pituitary." (PMID 33499110, 2021).
Short stature (1 paper, 2021). A height below that which is expected according to age and gender norms. "Entire gene deletions and/or mutations causing loss of protein function in SHOX, IGF1R, NPPC, and NPR2 have been reported in familial short stature with various degrees of severity 18,37–40." (PMID 33850126, 2021).
skeletal dysplasia (4 papers, 2014 to 2021). Any Mendelian diseases that affects growth and development of the skeleton. "Numerous loss-of-function mutations have now been reported in NPPC and NPR2, leading to profound skeletal dysplasias and short stature." (PMID 33499110, 2021).
tumor (4 papers, 2017 to 2025). "This intra-patient heterogeneity was replicated with Chromium data where we annotated two tumor subclusters for Tu_B3 corresponding to the area A and B with specific DE genes PLA2G2A and NPPC correspondingly." (PMID 40355415, 2025).
NPPC also shares sentences with these, for which no sentence is quoted: Sepsis (6 papers); Hypertension (3); cardiovascular disease (2); Epididymis (2); heart failure (2); Insulin resistance (2); myocardial infarction (2); Obesity (2); preeclampsia (2); pulmonary fibrosis (2); acromesomelic dysplasia (1); Acromesomelic dysplasia, Maroteaux type (1); angina pectoris (1); Anxiety (1); aortic valve disease (1); arachnodactyly (1); asthenozoospermia (1); atherosclerosis (1); brain glioma (1); Brugada syndrome (1); chondrodysplasia (1); chronic kidney disease (1); craniosynostosis (1); Crouzon syndrome (1); cystic fibrosis (1); delirium (1); Encephalopathy (1); epilepsy (1); Epiphyseal dysplasia (1); genetic diseases (1).
A further 15 diseases each share a sentence with NPPC in 1 paper.